IL6 (interleukin 6)
Diseases named in the same sentence as IL6 in open-access papers (continued):
Sharing a sentence is not in itself a finding about the gene and the disease.
viral infection (continued). "The skewed development of Th type responses in the presence of excessive IL-6 and IL-1 produced upon viral infection have been previously demonstrated with TMEV-infected DCs." (PMID 32727036, 2020). "Innate antiviral immune sensing via types I and III IFN leads to the production of pro-inflammatory cytokines (i.e. IL-6) within the first week after virus infection." (PMID 33123167, 2020). "IL6 is a major sign of systemic inflammation which can be induced by virulent virus infection such as PRV-Becker infection." (PMID 33198749, 2020). "The release of cytokines such as IFN-β, TNF-α, and IL-6 during viral infections plays a crucial role in the innate immune response against viruses." (PMID 31213553, 2019). "Further studies must unravel if upregulation of IL-6 in keratinocytes is correlated with keratinocyte transformation during the first stages of viral infection or with proliferation and malignancy that promote carcinogenesis." (PMID 31396215, 2019). "Since cytokine and chemokine release is the primary systemic response after bacterial or viral infection, we evaluated the LPS and ssRNA inflammatory responses by examining the induction of IL-6, IL-8, and CCL2." (PMID 31561453, 2019). "Genetically engineered rabies virus carrying the IL-6 gene in its genomic backbone has been used as an alternative model of experimentation to assess the relevance of IL-6 during viral infections." (PMID 31134045, 2019). "Additional evidence of IL-6's function during a virus infection was observed during lymphocyte choriomeningitis virus infection of mice where IL-6 and/or IL-6R activity was blocked using specific monoclonal antibodies." (PMID 31134045, 2019). "In this opinion note we would like to explore in more detail the biological functions of IL-6 in different virus models, and present our perspective regarding the debatable role of IL-6 during viral infections." (PMID 31134045, 2019). "The expression levels of IL-1β, IL-6, and IL-8 were significantly upregulated by virus infection, but were reduced in the compound-treated group." (PMID 31690059, 2019). "VSV and HSV-1 induced expression of mRNA transcripts of cytokines, such as Il1b, Il18, Il6, and Il12, were largely comparable between WT and Park2−/− cells after viral infection." (PMID 31229895, 2019). "Direct evidence supporting the importance of IL-6 during viral infections has been gathered in experimental infections using IL-6-deficient mice." (PMID 31134045, 2019). "We observed a surprising lower level of IL-6 upon challenge in mice that controlled influenza, because IL-6 is known as a cytokine that is involved in controlling virus infection." (PMID 31525249, 2019). "While several studies show the essential role of IL-6 to mount a proper immune response during some viral infections, others link this cytokine with exacerbation of viral disease." (PMID 31134045, 2019). "Further work is necessary to clarify the exact role of IL-6 during virus infections and the potential role of this cytokine to be used as a biomarker of viral virulence." (PMID 31134045, 2019). "In conclusion, there is plentiful evidence supporting a significant role of IL-6 during viral infections." (PMID 31134045, 2019). "PINK1 positively regulates the antiviral immune response through enhanced association with TRAF3 and IRF3 upon virus infection, which promotes IRF3 phosphorylation and results in increased IFN-β and IL-6 transcription." (PMID 31139191, 2019). "Targeting specific epigenetic mechanisms that influence expression of TNFα, NF-κB1a, IFNβ, and IL-12b and IL-6 provides a potential advantage during virus infection." (PMID 30483224, 2018). "IL6 has also been suggested to enhance the production of acute phase response proteins in virus infections." (PMID 30486363, 2018). "IL-2 and IL-6 were also found to be significantly up-regulated in other viral infections in the duck, such as in infections with AIV, DTMUV, and DEV." (PMID 29925406, 2018).
viral infection (continued). "Using proteomics, we have identified mouse BAL proteins that are differentially up-regulated by virus infection and overexpression of a immunomodulatory cytokine (IL6)." (PMID 30486363, 2018). "IFN-γ released from CD8 + cytotoxic T cells during a viral infection induced the secretion of IL-6 from BMMNCs51." (PMID 29784961, 2018). "In relation to CD8+ T-cell response, several reports showed that IL-6 plays a role in the promotion of effector response in viral infections or in vaccination using monophosphoryl lipid A/alum as adjuvant." (PMID 30364187, 2018). "The cytokine IL-6 plays an important role in both bacterial and viral infection, in which it can be both pro- and anti-inflammatory." (PMID 31022695, 2018). "Taken together, these results demonstrate the induction (in JAK1-expressing cells) of ISGs by cytokines (IL-6 and IFNα) and the augmentation of this induction by viral infection." (PMID 29441069, 2018). "During viral infection, inhibition of miR-451 expression elevates secretion of IL-6 and TNF-α in three types of primary dendritic cells." (PMID 29652844, 2018). "Noteworthy, the cytokines of crucial importance for clearing a viral infection, such as the Th1 cytokines IFNγ, and IL‐15, the pro‐inflammatory cytokines IL‐1β, IL‐6, TNFα, and TNFβ/lymphotoxin, were downregulated." (PMID 28805308, 2017). "Higher levels of IL-6 are associated with the exacerbations of COPD and increase the predictive accuracy of viral infection when combined with the clinical diagnosis." (PMID 28352642, 2017). "Here we find that early production of IL-6 is essential in promoting the regulation of immune responses after viral infection of the respiratory tract." (PMID 28953978, 2017). "In mice, not only the roles of IL-6 in viral infections are controversial, but the protective mechanisms mediated by IL-6 also vary." (PMID 29233145, 2017). "After virus infection or Poly (I:C) stimulation, FAF1gt/gt mice showed lower levels of cytokine production (IL-6 and IFN-β) than FAF1+/+ mice, which strongly supporting an impaired antiviral immune response, especially with respect to type I IFN signaling." (PMID 28542569, 2017). "In general, IL-6 is moderately increased in virus infections, lower than in Mycoplasma pneumoniae and bacterial infections." (PMID 29246125, 2017). "During MMTV infection via oral routes, LPS on MMTV virions promotes interlukin-6 (IL-6) secretion following virus infection of gut dendritic cells or macrophages, which in turn stimulate B cells that secrete IL-10." (PMID 29211815, 2017). "Interleukin-6 (IL-6) is a pro-inflammatory cytokine that is secreted by immune and inflammatory-related cells (T cells and macrophages) to stimulate responses to viral infection, trauma, and other tissue damage." (PMID 28946703, 2017). "The choice of cytokines was based on the known role of these molecules in the context of neuropathology, either by mediating inflammation (IL-6, IL-1β, TNFα, CCL5, CXCL1) and/or by their association to viral infections (IFNs)." (PMID 28330482, 2017). "Removal of either IL-6 or IL-27 enhances disease during viral infection, while restoration of IL-27 is sufficient to allow faster recovery." (PMID 28953978, 2017). "Viral disease in Ifitm3–/– mice was accompanied by elevated production of cytokines, most notably IL-6." (PMID 28240600, 2017). "LH-C blocked the early stages (0–2 h) of virus infection, it also suppressed virus-induced NF-kB activation and alleviated virus-induced gene expression of IL-6, IL-8, TNF-a, IP-10, and MCP-1 in a dose-dependent manner." (PMID 28235408, 2017). "Further experiments indicated that the production of type I IFNs in cells expressing the P2 and/or P3 RNAs was markedly elevated upon viral infection but the production of IL-6 was inhibited." (PMID 27250711, 2016).
viral infection (continued). "Although bacterial infections are commonly characterized by the induction of IL-6 and CRP, viral infections are generally associated with marked elevation in plasma IL-18 and ferritin with concomitant low circulating CRP levels." (PMID 27977798, 2016). "Using different animal models of viral infection,researchers found varying and transient degrees of impairment in Tfh cell numbers in theabsence of IL-6." (PMID 27096200, 2016). "In HIV infection of cultured cells, the STAT1 inhibitor fludarabine significantly decreased IL-6 expression indicating the importance of STAT1 signalling for IL-6 expression during viral infection." (PMID 25900439, 2015). "NF-κB is considered to be an important regulator of the expression of various genes during viral infection, particularly with regard to the secretion of the proinflammatory factors IL-6, IL-8, and COX-2." (PMID 26035722, 2015). "In conclusion, sIL-6R acts as an upstream regulatory factor for IL-32 during viral infection and promotes IL-6 production via IL-32, while IL-32 feedback inhibits the IAV-induced sIL-6R expression." (PMID 26087456, 2015). "For example, in virus infections, the expression of IL-6 in follicular B cells of the draining lymph node induces the production of critical cytokines such as IL-21; this is a necessary early event during the antiviral response." (PMID 26087456, 2015). "We found that proinflammatory cytokine (IL-5, IL-4, and IL-6) production was significantly increased later in the P17 (MA) viral infection process (at 5 dpi) compared with the parent (P0) virus infection." (PMID 26526113, 2015). "Viral infection of VSV-GFP or PR8-GFP and transfection of poly(I:C) or 5′ppp-dsRNA, a synthetic ligand for RIG-I, increased the secretion of IFN-β and IL-6 from MARCH5-deficient cells." (PMID 26246171, 2015). "These contradictory reports indicate an ambiguous role of TLR-induced IL-6 on host immune responses during viral infections." (PMID 25994622, 2015). "This study makes it clear that the induction of type I interferons during peripheral innate immune activation, mimicking viral infection, has effects on CNS-mediated behavioural and metabolic changes by IL-6-dependent and independent mechanisms." (PMID 25900439, 2015). "iNOS, COX-2, IL-6, IL-8, and TNF-α secretion by activating NF-κB pathway would cause cell injury, viral infection, inflammation, and tumourigenesis." (PMID 24683359, 2014). "Virus infection tends to promote proinflammatory cytokine production, and elevated production of IL-1β, IL-6, and IL-8 has been detected in patients with HFMD." (PMID 23554831, 2013). "Since RV infection of HBECs induces IL-6, measurement of IL-6 induction was used as a positive control marker to indicate viral infection." (PMID 23457497, 2013). "Infection with either pathogen resulted in expression of TNFα as well as IL-6, but SP induced more cytokine expression than the viral infection." (PMID 23421931, 2013). "The expression of IL-6 was similar in CEH with trypsin supplementation after infection at the early stage of viral infection, with a low expression level at 6 hpi and then a slight increase at 12 hpi." (PMID 24252391, 2013). "TNF-α and IL-6 are early cytokine mediators of inflammatory signaling and effectively amplify the host inflammatory response to viral infection." (PMID 23383181, 2013). "The significance of the induction of TNF-α and IL-6 expression following the TLR7/8-mediated response to ssRNA virus infection is not fully known." (PMID 24191131, 2013). "The basal level of IL-6 was 134.12 ± 0.23 pg/ml from mock infected cultures, while IL-6 was increased to 231.95 ± 2.79 pg/ml by 73% after viral infection (p<0.001)." (PMID 24278275, 2013). "During viral infection and associated TLR7/8 stimulation, macrophages produce various proinflammatory cytokines such as TNF-α and IL-6, which leads to an enhanced inflammatory response." (PMID 24191131, 2013).
viral infection (continued). "Firstly, It has been suggested that IL-17A induces TNF-α and IL-6 expression; therefore, we measured the TNF-α and IL-6 protein levels on the day 7, 60 and 90 post viral infection in the blood." (PMID 23977238, 2013). "Corneal cells are reported to produce a variety of cytokines during response to viral infection including IL-1α, IL-6, CXCL8, and low levels of IFN-γ." (PMID 22518343, 2012). "The mean levels of TNF-α and IL-6 cytokines were significantly higher in patients with active viral infection/coinfection (52.51 ± 15.13 pg/mL, 18.59 ± 3.56 pg/mL, resp)." (PMID 22927850, 2012). "Global microarray expression analysis displayed hallmarks of the early host response to viral infection and highlighted the prominent and rapid IL-1β/IL-6 mediated response." (PMID 22679491, 2012). "Both reagents also inhibited the induction of IL-6 and TNF-α mRNA expression in chorion cells after the virus infection and the secretion of IL-6 and TNF-α proteins from the cells [153, our unpublished data]." (PMID 22899878, 2012). "The production of IL-6 and IL-1β after virus infection can stimulate HPA axis, which leads to the release of GCs." (PMID 22719870, 2012). "Inasmuch as antigen presentation and cellular effector activity during a viral infection are regulated by cytokines, we evaluated the levels of serum IL-2, IL- 4, IL-6, IL-10, TNFα and IFNγ from LSIL patients and normal controls." (PMID 22642942, 2012). "We detected the presence of significantly higher levels of TNF-α and IL-6 in plasma samples from patients with active viral infection." (PMID 22927850, 2012). "Levels of IL-6 are known to correlate with the level of viral infection, and IL-6−/− mice have more severe HSV-1 encephalitis, with increased morbidity and death than IL-6+/+ mice." (PMID 23082204, 2012). "In the context of an acute viral infection, we observed complete redundancy in the roles for IL-6 and IL-21 in Tfh development at the peak of the effector CD4 T cell response." (PMID 21423809, 2011). "In CRH-knockout mice viral infection leads to an ACTH independent corticosterone response, which is associated with significantly higher IL-6 plasma concentrations compared to WT mice." (PMID 21466684, 2011). "BEAS-2B cells have been used extensively to study the effects of viral infection and activation of innate immunity on cytokine production, including the production of Interleukin 6 (IL6)." (PMID 22016778, 2011). "This strategy is used by poliovirus where protein 3A limits IL-6, IL-8 and β-interferon secretion during viral infection." (PMID 21931730, 2011). "In contrast, infection with the human apathogenic TCRV resulted in a strong up-regulation of several of these cytokines (IL-6, TNF-α and IL-10) in a manner that, for IL-6 and IL-10, was dependent on productive virus infection." (PMID 21572983, 2011). "In our patients including only presumptive viral infections, serum IL-6 was higher in febrile seizure children than in fever only controls." (PMID 21989210, 2011). "The production of these cytokines was further shown to be mechanistically distinct as both IL-6 and IL-10 production were dependent on productive virus infection while TNF-α production was also induced by UV-inactivated particles." (PMID 21572983, 2011). "C57BL/6 or IL-21−/− mice were treated with a neutralizing monoclonal antibody against IL-6 throughout the course of an acute viral infection (lymphocytic choriomeningitis virus, LCMV)." (PMID 21423809, 2011). "IL-6 together with IL-1 and TNF-α acts as an endogenous pyrogen by causing fever following viral infections." (PMID 21345237, 2011). "Takala and co-workers have studied 19 NE patients and 13 patients with other viral infections and detected an inverse correlation of serum IL-6 concentrations in NE patients with mean arterial pressure and minimum platelet count." (PMID 20500875, 2010).
viral infection (continued). "This conclusively shows that IL-6 regulates chronic disease severity by regulating the early immune response following viral infection." (PMID 19587788, 2009). "Specifically, IL-6 is an essential participant in the acute phase response following viral infection." (PMID 19587788, 2009). "Jego and colleagues showed that pDCs exposed to viral infection were able to activate the B-lymphocyte compartment and to promote the generation of plasma cells and/or plasmablasts in an IFNα-dependent and IL-6-dependent fashion." (PMID 19563672, 2009). "IL-6 was shown to be produced by corneal epithelial cells upon viral infection and acts as a chemoattractant since it recruits neutrophil granulocytes from the stroma of the cornea." (PMID 18769647, 2008). "Also, IL-10 was highly expressed, which has been involved in counteracting the pro-inflammatory effects of TNF-α and IL-6 while mitigating glutamate toxicity, factors responsible of neuropathogenic processes, including viral infections." (PMID 41474758, 2025). "The use of pro-inflammatory cytokines such as IL-6 or IFN-γ might provide a more representative model of viral infection–induced inflammation." (PMID 40660393, 2025). "An alternative discipline is the harnessing of host biomarkers such as C-reactive protein or Interleukin 6 (IL-6) to discriminate between groups of patients (e.g. CNS infections vs. other diseases and bacterial vs. viral infections) or to identify specific aetiologies." (PMID 40471671, 2025). "IL-6 has antiviral activity during viral infection, which might promote inflammation resolution and tissue remodeling." (PMID 40438117, 2025). "IL‐6 levels are elevated in viral infections, including both influenza and SARS‐CoV‐2." (PMID 39921246, 2025). "From an immunological perspective, vaccines and viral infections act as potent immune stimulants through activation of Toll-like receptors, antigen-presenting cells, and subsequent cytokine cascades, particularly IL-1β, IL-6, and TNF-α." (PMID 41155751, 2025). "In addition, viral infection promotes the release of some inflammatory cytokines or oncogenic cytokines, such as IL-1, IL-6 and VEGF." (PMID 40584044, 2025). "Furthermore, by inhibiting the MAPK signaling pathway, miquelianin prevents the overproduction of cytokines, such as IL-6 and IL-1β, induced by viral infection, thereby alleviating inflammatory responses." (PMID 40165966, 2025). "Inflammation in the heart after injury such as in a viral infection or other injury of the heart is largely mediated by pro-inflammatory cytokine release such as IL-6 by immune cells and fibroblasts, which further induce myofibroblast differentiation and fibroblast proliferation." (PMID 40181955, 2025). "However, high levels of IL-6 induce T helper 17 (Th17) cells to produce IL-17, which affect the immune defense system and prolong the duration of viral infection collectively." (PMID 40438117, 2025). "In agreement with GO analysis, the expression of immune‐related genes such as Ccl genes, Cxcl genes, Il6, Tnf, and Ifitm3 were further increased in the lungs of opt‐hACE2 mice after viral infection, highlighting a more pronounced immune response in these mice compared to the other mouse models." (PMID 39737574, 2025). "IL-10 could suppress the production of pro-inflammatory cytokines (e.g., TNF-α, IL-6), thereby limiting inflammation and tissue damage during acute viral infection (e.g., SARS-CoV-2, H1N1, respiratory syncytial virus (RSV))." (PMID 41156600, 2025). "Interleukin‐6 (IL‐6) drives pathological inflammation in viral infections such as COVID‐19, but its role in influenza, particularly with secondary AF infection, remains unclear." (PMID 40420617, 2025). "IL-1 and IL-6 are key pro-inflammatory cytokines released by the host during viral infection." (PMID 40626651, 2025).